EZH2 (enhancer of zeste 2 polycomb repressive complex 2 subunit)
Diseases named in the same sentence as EZH2 in open-access papers (continued):
Sharing a sentence is not in itself a finding about the gene and the disease.
tumor (continued). "Inactivation of the SMARCA4 gene, which encodes BRG1 protein, increases tumor invasiveness and affects sensitivity to conventional platinum-based chemotherapeutic agents but may increase tumor sensitivity to EZH2 inhibitors, CDK4/6 inhibitors." (PMID 40661782, 2025). "In addition to PRC2 components, we explored known HB tumor-associated genes to correlate with EZH2 expression patterns by tumor subtype." (PMID 40766612, 2025). "EZH2 expression is associated with tumor proliferation and poor prognosis in ACC patients." (PMID 40229247, 2025). "One such promising approach involves targeting PRC2 with EZH2 inhibitors, which could counteract the tumor-promoting effects of SMARCB1 loss." (PMID 40076599, 2025). "Accordingly, we propose that assessing IκBζ protein levels in tumor biopsies could serve as a diagnostic strategy to identify patients who would benefit from a combined immunotherapy with HDAC3 or EZH2 inhibitors." (PMID 40562773, 2025). "INI1 loss leads to EZH2 upregulation that promotes tumor growth." (PMID 39833894, 2025). "Its inclusion in HCC trials could explore its efficacy in mitigating tumor progression associated with EZH2 overexpression." (PMID 40074445, 2025). "In the present study, we aimed to assess the immunoexpressions of PD-L1 and EZH2 in ECs and evaluate their associations with key clinicopathological parameters, including patients’ age, tumour grade and stage, depth of myometrial invasion, histological subtype, and survival outcomes." (PMID 40310411, 2025). "DNMT1 and EZH2 are linked with low tumor-infiltrating CD8+ T cells and poor patient outcomes." (PMID 38715072, 2024). "Targeting EZH2 with specific inhibitors is particularly relevant in ARID1A-mutated cancers since EZH2 is known to influence tumor-infiltrating lymphocytes, thereby contributing to creating an immunosuppressive tumor microenvironment that facilitates immune evasion by tumor cells." (PMID 38893181, 2024). "Furthermore, the loss of EZH2 in T cells is associated with decreased anti-tumor immune surveillance." (PMID 38339323, 2024). "Our variant development of EZH2-score and tumor grading may be due to different methodical definitions of positive expression or staining." (PMID 40135141, 2024). "Additionally, the levels of enhancer of zeste homolog 2 (Ezh2) protein, a known factor promoting neoplasia in various tissues, have been linked to epigenetic silencing associated with the H3K27me3 modification." (PMID 38807590, 2024). "In addition, cancerous stem cells within SCC tumours, which improve the tumour's ability to invade tissues and migrate, have been shown to require increased EZH2 and its associated mark, H3K27me3, for optimal survival." (PMID 39624739, 2024). "Due to these diverse effects of EZH2 overexpression in tumor cells and TME-associated cells, the inhibition of EZH2 using epigenome-targeting agents may lead to a decrease in immunosuppression, thereby sensitizing tumors to immunotherapies." (PMID 38254784, 2024). "In diffuse large B-cell lymphoma and follicular lymphoma, recurrent point mutations in the catalytic SET domain (Y641) of EZH2 increase H3K27me3 activity, repressing the expression of tumor suppressor genes that mediate differentiation, cell-cycle inhibition, and apoptosis." (PMID 38886296, 2024). "Treatment with GSK126 (an EZH2 inhibitor) inhibits the growth of immune-deficient tumor cells." (PMID 38225241, 2024). "Tumor cells with loss of SMARCB1 demonstrate a constitutive EZH2 activation, and EZH2 inhibitors may modulate tumor immunogenicity and anti-tumor immune response." (PMID 38217715, 2024).
tumor (continued). "Furthermore, Ezh2-deficient Tregs acquired a pro-inflammatory phenotype that supported stronger anti-tumor immunity." (PMID 39007281, 2024). "Notably, during disease induction, the loss of EZH2 primarily exerts its tumor-suppressive effects by altering H3K27me3 at promoters rather than enhancers." (PMID 39655332, 2024). "Amongst the core subunits, EZH2 has been of particular interest within the literature due to its contribution toward drug resistance, and its overexpression is linked with both oncogenic and tumor suppression effects." (PMID 39768352, 2024). "Thus, both gain-of-function and loss-of-function mutations in EZH2 can result in chromatin remodeling, which in turn promotes tumor development by either repressing tumor suppressor genes or expressing oncogenes." (PMID 38473997, 2024). "Together, the EZH2 and KDM6A reports raise the possibility that H3K27 demethylation may underlie a female-biased tumor suppressor phenotype, while EZH2 and PRC2 activity may underlie a male-biased oncogenic phenotype." (PMID 38949020, 2024). "In addition to its role in tumor initiation and progression, EZH2 has also been implicated in drug resistance." (PMID 38036730, 2023). "Interestingly, the results showed that high EZH2 expression, which is significantly associated with a worse outcome, negatively correlated with the number of tumor-infiltrating mast, NK and Th17 cells." (PMID 36900330, 2023). "In addition, the overexpression of EZH2 mRNA and protein detected using qRT-PCR and immunohistochemistry was closely associated with tumor size, lymphatic invasion, and TNM stage." (PMID 36672374, 2023). "A potential marker for the susceptibility of tumor cells towards tazemetostat could be the mutation status of EZH2." (PMID 36900361, 2023). "High EZH2 expression level is associated with tumor expansion and cancer invasion." (PMID 37107631, 2023). "Likewise, deviant transcriptional regulation due to inhibition of EZH2 has been implicated in correlating with the immunogenicity of tumor cells and immune silencing in the tumor microenvironment." (PMID 37566041, 2023). "Additionally, they observed that high EZH2 expression was substantially linked with tumor stage, tumor size, histological differentiation, and lymph node metastasis." (PMID 37940644, 2023). "Thus, a novel anti‐cancer idea is to target tumour progression caused by PRC2‐mediated DNA hypermethylation through EZH2 inhibitors." (PMID 38050190, 2023). "In addition to its tumor-suppressive roles, EZH2 has been extensively implicated in the development of cancer." (PMID 38036730, 2023). "EZH2 immunoexpression was significantly associated with tumor grade (p = 0.001)." (PMID 37131568, 2023). "However, the decrease in EZH2 activity led to important changes in gene, protein and metabolite expressions associated with tumor survival pathways." (PMID 37511137, 2023). "Multiple arguments support the association between EZH2 expression and tumor immunogenicity, indicating that interfering with EZH2 expression may have an impact on the response to ICIs." (PMID 38077327, 2023). "Therefore, the treatment of EZH2‐dependent tumours after ARID1A mutation requires the inhibition of its interaction with proteins in addition to the inhibition of the methylesterase activity of EZH2." (PMID 36883311, 2023). "Moreover, epigenetic modifications associated with EZH2 contribute to the regulation of subsets of immune cells, including various T cells, innate immune cells such as tumor-associated macrophages (TAMs), myeloid-derived suppressor cells, NK cells, and so on." (PMID 35432300, 2022). "Supporting the assumption that the role of EZH2 in PTEN-depleted epithelial cells differs from that in PTEN-expressing epithelial cells, it was reported that loss of PTEN or activation of AKT switches the tumor suppressive role of EZH2 to an oncogenic function." (PMID 35269532, 2022).
tumor (continued). "Notably, it has been reported that overexpression of EZH2 is associated with tumor progression, aggressiveness, and poor prognosis in HCC." (PMID 35656182, 2022). "The expression of EZH2 was associated with several activated tumor-infiltrating immune cells." (PMID 36077742, 2022). "The expression of EZH2 has been associated with poor clinical outcomes in cancer patients, contributing to metastasis, metabolism, drug resistance, and angiogenesis, while conversely displaying tumor-suppressive functions." (PMID 35795673, 2022). "Moreover, the expression of histone methylase EZH2 is highly associated with suppressed IFN-γ signature in the tumor." (PMID 35693795, 2022). "Different EZH2-mediated gene promoter methylation have been demonstrated to increase the malignant phenotypes of cancer cells, which is related to the loss of tumor suppressor gene activities and results in stem cells or progenitor cells developing to cancer cells." (PMID 36316365, 2022). "Different authors have evaluated the clinical impact of EZH2 mutations in DLBCL in tumor samples." (PMID 36230571, 2022). "The synergy of a combined EZH2/ATM inhibition in BRCA1-deficient tumor cells could be demonstrated by using several small molecule inhibitors of EZH2 (GSK126, ZLD1039) and ATM (AZD1390, KU60019) that are currently at various stages of preclinical development." (PMID 35715861, 2022). "More importantly, only tumors treated with DZNep exhibited MYCN (and EZH2) loss even though 50 mg/kg of GSK126 was as capable as 3 mg/kg of DZNep in diminishing H3K27me3 expression within tumor cells (compare the H3K27me3 immunochemistry images between GSK126 and DZNep treatment)." (PMID 35013218, 2022). "EZH2′s high expression is associated with aggressive tumor subgroups, and poor prognosis." (PMID 36230787, 2022). "In addition, EZH2 has also been demonstrated associated with tumor resistance and its inhibitors can overcome resistance to immunotherapy." (PMID 36195655, 2022). "Interestingly, recently CAFs-enhanced EZH2 expression has been disclosed and is associated with migration ability of tumor." (PMID 36401232, 2022). "Moreover, high expression of EZH2 is reported to be significantly associated with advanced stage and is a predictor of aggressive tumor characteristics and frequent distant metastasis." (PMID 36230787, 2022). "Abnormal expression of EZH2 can cause neurodegenerative and neoplastic diseases." (PMID 35846885, 2022). "Furthermore, in the immunocompetent LLC tumor model, the inhibition of EZH2 causes tumor regression and enhances the CD8+T cell infiltration." (PMID 35912007, 2022). "In addition, primary tumor cells containing Enhancer of Zeste 2 Polycomb Repressive Complex 2 Subunit (EZH2+)/E-cadherin- markers are highly associated with tumor recurrence." (PMID 35800367, 2022). "Besides tumour grade, our results verified that EZH2 immunoexpression was significantly associated with other clinicopathological parameters, such as age and IDH1 R132H protein mutant status." (PMID 36292072, 2022). "However, as observed by us and others, selective loss of H3K27me3 function of EZH2 poses a significant inhibitory influence on cancer cell migration and tumor metastasis." (PMID 36446780, 2022). "Notably, aberrant EZH2 expression has been associated with diverse cancers concerning both oncogenic and tumor suppression functions." (PMID 36446780, 2022). "The EZH2 gene is coded in chromosome 7, and its mutations have been described in both myeloid and lymphoid malignancies, as well as in solid tumours, where they have been recurrently associated with more advanced tumour stages and metastatic disease." (PMID 35626091, 2022).
tumor (continued). "These suggest that tumor cells expressing EZH2 and FOXM1 may be pathological associated with CAFs in GC." (PMID 36401232, 2022). "Similarly, in muscle invasive bladder cancer models, EZH2 inhibition limits the proliferation of tumor cells in the context of KDM6A and SWI/SNF mutations." (PMID 36135315, 2022). "This suggested that EZH2 and G9a were associated with tumor malignancy." (PMID 35409271, 2022). "In addition to overexpression, EZH2 mutation was also confirmed to be highly correlated with tumor progression." (PMID 33761979, 2021). "Indeed, Ezh2-deficient tumor infiltrating Treg cells showed an increased production of the pro-inflammatory cytokines TNF-α, IFN-γ, and IL-2 and a reduced expression of IL-10." (PMID 34262562, 2021). "Consistent with our findings, one study showed that an elevated level of EZH2 was associated with over proliferation of tumor cells and worse prognosis and may have clinical utility for distinguishing indolent PRAD from aggressive disease with a fatal course." (PMID 33869043, 2021). "However, it is conceivable that, in in vivo treatment, both tumor cells and NK cells and their precursors will be exposed to the same drug, both becoming susceptible to the effect of EZH2 inhibitor, and thus leading to different results." (PMID 33467134, 2021). "Interestingly, integration with ENCODE data revealed that proximal tumor-gained promoters were associated with EZH2 and SUZ12 occupancies, which are the core components of polycomb repressive complex 2 (PRC2)." (PMID 33916417, 2021). "Therefore, NFATC1 induction by EZH2 loss is implicated in increased tumor aggressiveness and progression in BLBC patients." (PMID 34845197, 2021). "Moreover, integration with ENCODE data revealed that proximal tumor-gained promoters were associated with EZH2 and SUZ12 occupancies, which are the core components of PRC2 (polycomb repressive complex 2)." (PMID 33916417, 2021). "Along with epigenetic silencing of tumor-suppressor genes, in different types of cancer cells, EZH2 upregulation is linked with the transcriptional repression of genes that confer immunogenicity (e.g., MHC I and II) and support the recruitment of effector T cells (e.g., CXCL9 and CXCL10)." (PMID 33922336, 2021). "Moreover, blocking EZH2 expression by the pharmacological inhibitor CPI-1205 in MB49 tumor-bearing mice was associated with a better survival when combined with anti-CTLA-4." (PMID 34262562, 2021). "Therefore, the status of the BRAF V600E mutation with an EZH2 gene copy number variation can be used as a potential tumor therapeutic target." (PMID 34001246, 2021). "Thus, our current findings advance the field by identifying an additional layer of regulation of EZH2 phosphorylation and associated tumor biology." (PMID 33593912, 2021). "Thus far, the impact of EZH2 inhibition on human tumor-associated macrophages (TAMs) accumulation and functional activation is still largely unexplored." (PMID 33922336, 2021). "Exposure of F-box and WD repeat domain-containing 7 (FBW7) to EZH2 causes the degradation of EXH2 in PC cells and inhibits tumour migration and invasion, indicating its role as a ligase of EZH2 that regulates EZH2 protein levels in PC and furthermore, its potential as a treatment strategy." (PMID 33673153, 2021). "Loss of Ezh2 or inhibition of its enzymatic activity with small molecules in both mouse and human hematopoietic stem and progenitor cells enhanced NK cell expansion and cytotoxicity against tumor cells through upregulation of CD122 and NKG2D." (PMID 34017344, 2021). "Since the activation of NF-κB signaling is critical to the survival of tumor cells, we speculate that inhibition of EZH2 in PCa cells may cause feedback activation of NF-κB signaling." (PMID 33794893, 2021).
tumor (continued). "Given as the EZH2 mutation remodels the FL tumor cells’ interactions with the tumor microenvironment, it is intriguing to speculate that combinational approaches of tazemetostat with other targeted therapies may be synergistic." (PMID 33671658, 2021). "Furthermore, we observed the association between proximal tumor-gained promoters with EZH2 and SUZ12 occupancies." (PMID 33916417, 2021). "Besides, the expression of EZH2 also involved in acquiring M2 phenotype of tumor-associated macrophages (TAMs), activation of dendritic cells (DCs) to mediate epigenetic modification in immunotherapy." (PMID 34077304, 2021). "Since both JMJD6 and EZH2 associate independently with poor prognosis in cancer, the results were extrapolated to clinical samples, and their expression and association was studied in tumor and normal samples; and in publicly available RNA-Seq databases." (PMID 33246425, 2020). "Moreover, due to the function of PRC2 in maintaining transcriptional gene silencing, EZH2 mutations always exert both oncogenic and tumor-suppressive effects and both gain-of-function and loss-of-function behavior." (PMID 33163485, 2020). "The selective EZH2 inhibitor tazemetostat demonstrated objective response rates in 77% of FL patients with EZH2 mutations in an ongoing phase II clinical trial, with EZH2 mutations detected in both tumor tissue and plasma representing the only predictive biomarker of therapy response." (PMID 32668764, 2020). "Therefore, our results indicate that ZMYND8 in association with the corepressor complex (KDM5C and EZH2) transcriptionally represses the poised tumor-promoting genes by removing H3K4Me3 and reinstating H3K27Me3 levels." (PMID 33323928, 2020). "Interestingly, the lncRNA UCA1 also guides EZH2 to the gene loci pf p21 and E-cadherin, causing epigenetic gene silencing of these tumor suppressors." (PMID 32331331, 2020). "Some of these studies demonstrated an inverse correlation between miR-144 and EZH2 expression in samples of patients, with miR-144 usually downregulated and EZH2 upregulated, as well as a strong correlation with the aggressiveness of the associated tumor." (PMID 33233721, 2020). "Additionally, the loss-of-function mutations re-sensitize different tumor types to various drugs, like EZH2-, PARP-, HDAC-, HSP90- or ATR-inhibitors." (PMID 32272809, 2020). "EZH2 inhibitors have been reported to sensitize variant tumor cells to anticancer drugs." (PMID 33276757, 2020). "A high expression of EZH2 is inversely associated with the tumor infiltration of CD8+ T cells." (PMID 32708698, 2020). "Low‐glycemic tumor microenvironments have been found to decreased T cell viability, which are associated with the low expression of zeste methyltransferase enhancer homolog 2 (EZH2) and decreased glycolytic function." (PMID 34766109, 2020). "Notably, EZH2 overexpression is reportedly associated with tumor progression and aggressiveness in HCC." (PMID 33180829, 2020). "This suggests that MEG3 might serve as a tumor-suppressive lncRNA in BTC via its ability to cause degradation of EZH2." (PMID 32331331, 2020). "Depending on the cellular environment and the activated oncogenic pathways, the changes in epigenetic modifications caused by EZH2 defects may lead to tumor progression through various mechanisms." (PMID 33299862, 2020). "However, attention should be paid to the side effect on immune system and clinical effect related to malignancies due to the interplay between EZH2 and other miRNAs implicated in the drug resistance and tumor progression." (PMID 32657761, 2020). "The level of H3K27 monomethylation and dimethylation in cancer cells and tumor tissues with heterozygous EZH2 mutations at Y641 and A677 is decreased, while the level of H3K27 trimethylation is increased, resulting from the changed substrate preference of the mutant enzymes." (PMID 30984620, 2019).